RAB36 (RAB36, member RAS oncogene family)
Description:
The small GTPases Rab are key regulators of intracellular membrane trafficking, from the formation of transport vesicles to their fusion with membranes. Rabs cycle between an inactive GDP-bound form and an active GTP-bound form that is able to recruit to membranes different sets of downstream effectors directly responsible for vesicle formation, movement, tethering and fusion.
Tractability: PROTAC: its protein half-life has been measured.
Gene: Protein-coding gene on chromosome 22 (23,145,366 to 23,165,663, forward strand). Ensembl gene ENSG00000100228.
Subcellular location: Golgi apparatus membrane
Subcellular location (Human Protein Atlas): Vesicles
Pathways (Reactome):
Metabolism of proteins: RAB geranylgeranylation
Vesicle-mediated transport: Intra-Golgi traffic
Gene Ontology:
Molecular function: protein binding; GTP binding; GTPase activity; G protein activity
Cellular component: Golgi apparatus; Golgi membrane
Genetic constraint (gnomAD): Loss-of-function variants: 37 observed, 41.5 expected, observed/expected ratio (o/e) 0.89, 90% interval 0.69 to 1.17. The upper end of that interval is the gene's LOEUF score, 1.17, which puts it in group 5 of 6, group 1 being the genes least tolerant of losing a copy. Missense variants: 308 observed, 359.23 expected, observed/expected ratio (o/e) 0.86, 90% interval 0.78 to 0.94. Synonymous variants: 133 observed, 141.85 expected, observed/expected ratio (o/e) 0.94, 90% interval 0.81 to 1.08.
Homologues: Orthologues: chimpanzee RAB36 (99% identical), macaque RAB36 (97% identical), guinea pig RAB36 (89% identical), pig RAB36 (88% identical), mouse Rab36 (88% identical), rat Rab36 (88% identical), rabbit RAB36 (76% identical), tropical clawed frog rab36 (66% identical), zebrafish rab36 (60% identical), dog RAB36 (56% identical), Drosophila melanogaster RabX5 (40% identical). Paralogues in human: RAB34 (56% identical), RAB13 (28% identical), RAB11B (28% identical), RAB11A (27% identical), RAB25 (27% identical), RAB6A (27% identical), RAB14 (26% identical), RAB1B (26% identical), RAB37 (26% identical), RAB43 (26% identical), RAB6B (26% identical), RAB1A (25% identical), and 56 more.
Diseases named in the same sentence as RAB36 in open-access papers:
RAB36 is named in the same sentence as 10 diseases in open-access papers, as found by Europe PMC text mining. Sharing a sentence is not in itself a finding about the gene and the disease. The quoted sentences say what the papers report.
glioma (2 papers, 2023 to 2024). A benign or malignant brain and spinal cord tumor that arises from glial cells (astrocytes, oligodendrocytes, ependymal cells). "To further verify the correlations of PD-L1 with FMOD, MXRA5 and RAB36, we established a mouse model using CT2A and GL261 mouse glioma cells." (PMID 39513108, 2024). "When GII/GIII-IDHmut gliomas were compared to GIV gliomas, significant differences of DNA methylation in the promoters of S100A2, RAB36, RIN1, UPP1, and VIM were found." (PMID 36850002, 2023).
colon cancer (1 paper, 2022). "Similar to what was observed in cells, RAB36 was highly expressed in liver metastatic colon cancer tissues compared to primary colon cancer tissues." (PMID 36224588, 2022).
colorectal cancer (1 paper, 2023). A primary or metastatic malignant neoplasm that affects the colon or rectum. "Consequently, the stability of RAB36 mRNA decreases, leading to a reduction in RAB36 protein expression, which inhibits the metastasis of colorectal cancer." (PMID 38203348, 2023).
malignant rhabdoid tumors (1 paper, 2021). "It was reported that the depletion of RAB36 leads to G1 cell cycle arrest, disruption of mesenchymal-epithelial transition, and simplification of the malignant rhabdoid tumors dissemination." (PMID 34446027, 2021).
renal carcinoma (1 paper, 2024). A carcinoma arising from the epithelium of the renal parenchyma or the renal pelvis. "RAB36 has also been shown to be highly expressed in all of the tissues assayed, most notably in the testis and brain, and is observed to prognostic factor in multiple cancer lines, particularly in renal cancer." (PMID 38347632, 2024).
tumor (4 papers, 2020 to 2024). "RT-PCR results showed that the expression of FMOD, MXRA5 and RAB36 in tumor tissues of most patients was higher than that in paracancerous tissues." (PMID 39513108, 2024). "Moreover, LGG tumors with CD302 or FABP5 overexpression highly expressed some oncogenes, including GPR65, PIK3CG, CHI3L1, and RAB36, which were reported to promote tumor growth and metastasis." (PMID 32775301, 2020). "We determined gene expression in nine cancerous and tumor- adjacent tissues from patients with GBM and found that expression levels of FMOD, MXRA5, and RAB36 in the cancer tissue was higher than those in the para-cancerous tissue in most patients." (PMID 39513108, 2024). "circPPFIA1s upregulate tumor-suppressing CDX1 by decoying CDX1-targeting miR-155-5p and downregulate oncogenic RAB36 by sequestering HuR." (PMID 36224588, 2022). "circPPFIA1s upregulated tumor-suppressing CDX1 expression and conversely downregulated oncogenic RAB36 by decoying miR-155-5p and by sequestering HuR, respectively." (PMID 36224588, 2022). "RAB36, a member RAS oncogene family, is upregulated in various types of cancers and may be closely related with tumor development and metastasis." (PMID 36224588, 2022). "As tumor suppressors, circPPFIA1-L and -S negatively control the metastatic potential of CRC via two pathways: as a sponge of miR-155-5p, upregulating CDX1 expression; and as a sponge of HuR, downregulating RAB36 expression." (PMID 36224588, 2022).
cancer (3 papers, 2022 to 2025). A tumor composed of atypical neoplastic, often pleomorphic cells that invade other tissues. "RAB36 has been implicated in promoting CRC progression and invasion, while its knockdown in cancer cells resulted in reduced metastatic potential." (PMID 40041860, 2025).
kidney disease (1 paper, 2024). "Thus, we hypothesize that kidney disease in the Tiwi cohort may have been affected indirectly via altered RAB36 expression or a RAB36 gene product." (PMID 38347632, 2024).
RAB36 also shares sentences with these, for which no sentence is quoted: infection (1 paper); oligodendroglioma (1).